KRAS (KRas proto-oncogene, GTPase)
Diseases named in the same sentence as KRAS in open-access papers (continued):
Sharing a sentence is not in itself a finding about the gene and the disease.
cancer (continued). "Previous studies have suggested upregulation and functional roles for miR21, miR450b-5p, and miR30c in response to oncogenic KRAS in cancer." (PMID 31874105, 2020). "For dysregulated KRAS-RalB-NF-κB signaling in FGβ3 cells, galectin-3 plays a critical role in clustering integrin αvβ3 to induce KRAS and enable multiple processes in cancer cells." (PMID 32514015, 2020). "Still, some novel FTIs, when combined with other inhibitors such as geranylgeranyl-transferase inhibitors, showed potent anti-cancer activities in KRAS-driven pancreatic tumors." (PMID 32548736, 2020). "Gene set enrichment analysis showed that these gene sets are significantly enriched in cancer-related pathways, such as Kirsten rat sarcoma viral oncogene homolog (KRAS) signaling." (PMID 33149738, 2020). "This tool will offer new research applications to study KRAS biology and paves the way for novel discoveries in the cancer field." (PMID 32887255, 2020). "This review summarizes the current knowledge about the therapeutic approaches of KRAS-mutated LADC and provides an update on the most recent advances in KRAS-targeted anti-cancer strategies, with a focus on potential clinical implications." (PMID 32548736, 2020). "The data show that cancer-promoting pathways such as KRas activation can alter mechanoresponsiveness at a very early stage in the signaling pathway (in less than 30 s)." (PMID 33020304, 2020). "The most important member of RAS proteins is KRAS, which represents one of the most important drivers of cancer." (PMID 32610656, 2020). "Our results provided evidence suggesting that the formation of NETs was induced by KRAS-mutant cancer-derived exosomes through enhancement of IL-8." (PMID 32228650, 2020). "Data on genetic alterations in seromucinous carcinoma are limited, although one international study showed mutations in ARID1A, KRAS, PIK3CA, and PTEN in 16%, 70%, 37%, and 19% of seromucinous carcinoma, respectively, based on analysis of 32 cases." (PMID 32023964, 2020). "Our data confirms this phenomenon because of eight KRAS amplified samples, six were liver metastases and only two were primary carcinomas (P < 0.0001, the chi square test with Yates correction)." (PMID 32350415, 2020). "Considerable efforts have been made to potentiate the efficacy of chemotherapy in KRAS-mutant cancer." (PMID 31612108, 2019). "RAS subfamily comprises the ubiquitously expressed human RAS proteins KRAS4A, KRAS4B (the two KRAS splice variants), HRAS, and NRAS, which are frequently mutated in cancer." (PMID 31681616, 2019). "Attempts at targeting RAS function using farnesyl transferase inhibitors also proved to be ineffective, failing to demonstrate antitumor activity in KRAS-driven cancers." (PMID 30683716, 2019). "The Ras gene family has three members, including KRAS, which has the greatest impact on human cancer." (PMID 30347501, 2019).
cancer (continued). "Collectively, these findings identify ADAM17 as a druggable target for oncogenic KRAS‐driven LAC and provide the rationale to employ ADAM17‐based therapeutic strategies for targeting KRAS mutant cancers." (PMID 30833304, 2019). "KRAS-dependent cancer cell growth is inhibited by disrupting phosphatidylserine transport to the plasma membrane by genetic knockdown of lipid exchangers ORP5 and ORP8 or by inhibition of PI4KIIIα." (PMID 31451509, 2019). "Our results with ORP5 and ORP8 knockdown as well as with PI4KIIIα inhibition have possible implications for cancer therapy in KRAS-mutant tumors." (PMID 31451509, 2019). "Almost all were initially filtered as germline events, as many well-known actionable cancer mutations (e.g., BRAF V600E and KRAS G12C) are present in the dbSNP database and occurred at frequencies that fell within our exclusion criteria." (PMID 31262303, 2019). "In contrast, more immunogenic cancer cells with endogenous JAK2 deletion and BRAF or KRAS mutation (RKO and HCT116) displayed tolerance to momelotinib, reducing the combinatory effect." (PMID 30670049, 2019). "While the mutation profile of each individual cancer will be unique, certain mutation patterns are associated with CRC (e.g. APC, KRAS, and BRAF)." (PMID 31824558, 2019). "The delta subunit of rod-specific photoreceptor cGMP phosphodiesterase (PDE6D) mediates antegrade trafficking of KRAS to the cell membrane implicating its potential crucial role in cancer." (PMID 30901922, 2019). "RAS family genes, including HRAS, KRAS and NRAS, are the most common oncogenes in human cancer, and encode extremely similar proteins made up of chains of 188 to 189 amino acids." (PMID 30971271, 2019). "Understanding oncogenic KRAS cellular reprogramming has the potential to reveal novel strategies to control metastasis in KRAS-driven cancers." (PMID 31681587, 2019). "Cancer cells of KRAS-dependent tumors use autophagy in order to support the growth of cancer cells under stressful conditions in hypoxic regions of tumors." (PMID 31013961, 2019). "Among the RAS proteins - HRAS, NRAS, and the alternatively spliced KRAS4a and KRAS4b (referred from hereon as KRAS), mutations in KRAS are responsible for 86% of RAS-driven cancers including pancreatic, colorectal, and lung cancers." (PMID 31324887, 2019). "Alterations in any of these RAS family genes is associated with poor patient prognosis in pan-cancer analyses, and RAS pathway gene alterations frequently co-occur with the exception of KRAS-BRAF and KRAS-NRAS gene pairs, which are mutually exclusive." (PMID 31681559, 2019). "Despite its great potential as a cancer target, KRAS has proved to be very difficult to inhibit in a therapeutic setting." (PMID 30683716, 2019). "As expected, known cancer proteins BRAF, PIK3CA, KRas, Akt1, IDH1, and NRas showed the highest hotspot mutation scores in the TCGA dataset." (PMID 31345222, 2019). "Investigation of the relative expression of KRAS also showed higher expression in the AGS cancer cell line." (PMID 31330954, 2019). "KRAS-driven cancers employ micropinocytosis to scavenge nutrients from the extracellular environment." (PMID 31681559, 2019). "Since the KRAS4B isoform is the more common variant associated with human cancer, the KRAS4B sequence was cloned into the BirA* fusion construct and unless otherwise noted, KRAS in this manuscript refers to KRAS4B." (PMID 31712554, 2019).
cancer (continued). "This mitochondrial metabolism has been shown to be essential for anchorage-independent cell growth in KRAS-driven cancers by promoting generation of reactive oxygen species, which modulate ERK signaling." (PMID 31681559, 2019). "Among the CASEs, 26 events were identified to generate new isoforms in 22 cancer drivers, such as KRAS, SMARCA4 and FBXW7." (PMID 31695792, 2019). "Since the discovery of PDEδ-mediated KRAS solubilization, KRAS recycling and trafficking has come to attention as a potential cancer target, with recent efforts devoted to targeting PDEδ." (PMID 31712554, 2019). "Our study identifies ADAM17 as a key cooperating factor and druggable target in oncogenic KRAS‐driven LAC and thus provides the rationale to employ ADAM17‐based therapeutic strategies for targeting oncogenic KRAS‐addicted cancers." (PMID 30833304, 2019). "In KRAS mutant cancers, targeting of MEK with trametinib led to compensatory signaling through fibroblast growth factor receptor 1 (FGFR1)." (PMID 31681559, 2019). "Cleaved PARP immunoblot assay revealed that treatment with AZ628 or BP-1-102 single selectively increased cleaved PARP protein levels in KRAS mutant cancer cells, while these inhibitors combination significantly induced cleaved PARP expression in these cells." (PMID 31484165, 2019). "Nevertheless, there was a high accordance between KRAS mutation status in EBC–DNA and cancer tissue in NSCLC patients." (PMID 30368666, 2019). "To further confirm that miR-873 mediates its inhibitory effects through downregulation of KRAS, we performed rescue experiments using mutated KRAS clone constructs to overexpress KRAS protein in PANC1 and MDA-MB-231 cancer cells." (PMID 30654191, 2019). "Several groups are currently developing methods to detect somatic mutations with the aim of discovering markedly higher cell-free DNA (cfDNA) concentrations in the blood of patients with cancer, in particular, KRAS from plasma and serum." (PMID 31383871, 2019). "ARS-853 potently suppresses the growth of cancer cells bearing G12C mutant KRAS, while cancer cells that express non-G12C mutants (i.e. G12D, G12S, G12 V, G13D, Q61K, etc.)are resistant to ARS-853." (PMID 30971271, 2019). "The data suggest the complexity of STAT3 in tumorigenicity and treatment responses of cancers with oncogenic KRAS." (PMID 31296870, 2019). "KRAS signaling sustains cancer cells under conditions of nutrient stress by activating an NRF2-ATF4 axis to increase amino acid transport and protein biosynthesis, preventing apoptotic cell death through increased asparagine synthase activity." (PMID 31681559, 2019). "Although oncogenic mutations in the three major Ras isoforms, KRAS, HRAS and NRAS, are present in nearly a third of human cancers, therapeutic targeting of Ras remains a challenge due to its structure and complex regulation." (PMID 31497244, 2019). "Following this discovery, oncogenic KRAS mutations were identified as a common feature of LAC (accounting for 33% of all LAC patients) and other human cancers." (PMID 31438559, 2019). "Three simultaneously published studies signal a resurgence of interest to inhibit autophagy in KRAS-driven cancer." (PMID 31612108, 2019). "The RAS family of proto-oncogenes comprises HRAS, KRAS, and NRAS, which are among the most mutated genes in human cancers." (PMID 31852884, 2019). "In turn, these perturbations of KRAS PM interactions lead to reduced proliferative and tumorigenic capacity of KRAS-mutant cancer cells." (PMID 31451509, 2019). "Similar efforts identified a high-affinity allosteric KRAS inhibitor that impairs KRAS signaling and cancer cell growth in cells bearing several distinct types of KRAS activating mutation." (PMID 31681559, 2019).
cancer (continued). "AZD4785 is a potent and selective therapeutic KRAS cEt-ASO currently under clinical development for the treatment of cancer." (PMID 30927008, 2019). "In mesenchymal-like KRAS-mutant cancer cells, reactivation of MEK and AKT was dominantly driven by FGFR1." (PMID 31612108, 2019). "Altogether, the three human Ras genes, KRAS, NRAS, and HRAS, are among the most frequently mutated oncogenes in cancer, cumulatively estimated at 25–30% of all malignancies." (PMID 31712554, 2019). "The members of the RAS subfamily of GTPases, which includes KRAS, HRAS, and NRAS, are frequently mutated in cancer." (PMID 31681616, 2019). "Our data show that wild-type EGFR plays a significant role in KRAS-mutant NSCLC cancer cells and revealed CXCR7 upregulation as a potential survival mechanism in KRAS-mutant cells upon EGFR loss." (PMID 30935067, 2019). "Recent work characterizing small non-coding RNAs in cancer identified an unexpected role for specific snoRNAs in the control of KRAS-driven tumorigenesis." (PMID 31712554, 2019). "Amplification of the oncogenes ERBB2, CDK6, MDM2 affected dependency, as did point mutations in PIK3CA, KRAS, NRAS, VHL and BRAF, validating our approach to highlight genes with significance in cancer." (PMID 30803482, 2019). "The concordance ratios of KRAS sequence in codon 12 between EBC–DNA and cancer were 18/19 for NSCLC patients and 11/12 for KRAS mutation positive NSCLC." (PMID 30368666, 2019). "We show that these DARPins specifically inhibit KRAS/effector interactions and the dependent downstream signalling pathways in cancer cells." (PMID 31197133, 2019). "The family of RAS genes (KRAS, HRAS, and NRAS) are the first oncogenes identified, and are the most frequently mutated genes in human cancer cells, including lung, pancreatic and colorectal cancers." (PMID 31438559, 2019). "The second probable mechanism of controlling cancer cells by magnetic nano-oleuropein is through the increased relative expression of KRAS." (PMID 31330954, 2019). "Insight into KRAS-driven CRCs will stimulate new research to find the best approach to treat this aggressive type of cancer, encouraging further evaluations of novel combination strategies including PI3K/mTOR/AKT inhibitors." (PMID 31771279, 2019). "Of note, three of the cancer cell lines, Capan-2, MIA PaCa-2, and Panc-1, have oncogenic mutations in the KRAS gene, whereas BxPC-3 has wild-type KRAS." (PMID 31134894, 2019). "Previous studies commonly reported that mutations in oncogenes such as KRAS, PIK3CA, BRAF were associated with clinical outcomes in various cancers." (PMID 30871151, 2019). "Oncogenic KRAS induces the expression of Sonic Hedgehog (SHH) in cancer cells, whilst SHH induces expression of the transcription factor GLI family zinc finger 1 (GLI1) in fibroblasts." (PMID 31847096, 2019). "Concordantly, ORP5 or ORP8 depletion significantly reduced proliferation and anchorage-independent growth of multiple KRAS-dependent cancer cell lines, and attenuated KRAS signaling in vivo." (PMID 31451509, 2019). "Pharmacological induction of ER stress in LKB1/KRAS double mutant cancer cells triggers proapoptotic unfolded protein response and ROS-induced cell death." (PMID 31781355, 2019). "It has also been found that vitamin C therapy can be a possible treatment for pancreatic cancer, another typically lethal cancer driven by KRAS." (PMID 31357509, 2019). "Cancer cells that become dependent on KRAS-driven metabolic adaptations are sensitive to the inhibition of these metabolic routes, revealing novel therapeutic windows of intervention." (PMID 31544066, 2019). "For example, the smaller changes in representation for KRAS gRNAs 1 and 6 over the course of multiple cancer cell line screens are appropriately captured in the differences of the posterior distributions." (PMID 30674557, 2019).
cancer (continued). "We show that this peptide-based NP is avidly taken up by cancer cells in vitro, can deliver KRAS-specific siRNA, inhibit KRAS expression, and reduce cell viability." (PMID 31413817, 2019). "Antagonism between SNORD50A/B RNAs and specific SNARE proteins thus controls KRAS localization, signaling, and tumorigenesis, and disrupting SNARE-enabled KRAS function represents a potential therapeutic opportunity in KRAS-driven cancer." (PMID 31712554, 2019). "This study showed that BP-1-102 markedly increased the protein levels of p-MEK and p-ERK in KRAS mutant cancer cells, suggesting that STAT3 inhibitor can result in MEK and ERK up-regulation." (PMID 31484165, 2019). "Some of these fragments derived from cancer-related genes, including KRAS, were among the most upregulated exRNAs in cancer patients as compared to normal donors." (PMID 31481608, 2019). "KRAS G12/13 is a driver in tumors and in combination with its high frequency in cancers makes KRAS an ideal target for immunotherapies." (PMID 31803176, 2019). "Expression of GLUT1 is regulated by several oncogenic signaling pathways, including oncogenic KRAS and is increased in cancer cells." (PMID 31288436, 2019). "Their presence in almost all major cancers makes them a highly valued therapeutic target, in particular the KRAS gene, since it has been identified as one of the most frequently mutated oncogenes." (PMID 30683716, 2019). "High FGFR2 was associated with increased frequency of vascular invasion (p=0.047), high MET with distal location of the cancer (p=0.012) and low KRAS with presence of distant metastasis (p=0.022)." (PMID 31602266, 2019). "This would be a promising way to isolate KRAS selective small inhibitors for the treatment of KRAS mutant cancers." (PMID 31197133, 2019). "Inhibition of KRAS-enhanced macropinocytosis represents another possibility to target mutant cancer cells by interfering with their ability to internalize extracellular fluids-containing nutrients." (PMID 31847096, 2019). "Small nucleolar RNAs, SNORD50A/B are frequently deleted in cancers and can inhibit KRAS but by unclear means." (PMID 31712554, 2019). "It has previously been shown that TNKS inhibition sensitizes KRAS mutant cancer cells to growth inhibition by MEK inhibitors, also in cell lines whose proliferation rate is unaffected by single TNKS inhibitor treatment." (PMID 30717152, 2019). "This study utilized A549 cells, a KRAS-driven cancer cell line derived from alveolar epithelial cells." (PMID 30833945, 2019). "Overall, across the large panel of colorectal cell lines with a range of genetic backgrounds, combined MEK- and PI3K-inhibition is highly synergistic, particularly in KRAS mutant cancers." (PMID 30905967, 2019). "In particular, we showed that miR-873 regulates important hallmarks of cancer, including cell proliferation, apoptosis, and invasion, through the targeting of multiple oncogenic routes involving KRAS-induced ERK/AKT signaling." (PMID 30654191, 2019). "The increased uptake of DHA into the KRAS or BRAF mutant cancer cells leads to the rapid conversion of DHA to vitamin C, resulting in the depletion of GSH and NADPH and an increase in ROS that cause DNA damage." (PMID 31357509, 2019).